CCT5 (chaperonin containing TCP1 subunit 5)
Diseases named in the same sentence as CCT5 in open-access papers (continued):
Sharing a sentence is not in itself a finding about the gene and the disease.
esophageal adenocarcinoma (1 paper, 2025). A malignant tumor with glandular differentiation arising predominantly from Barrett mucosa in the lower third of the esophagus. "Furthermore, CCT5 genetic alterations were greater than 8% in the EAC (Esophageal Adenocarcinoma), BLCA, and LUAD samples." (PMID 40274875, 2025).
glioma (1 paper, 2025). A benign or malignant brain and spinal cord tumor that arises from glial cells (astrocytes, oligodendrocytes, ependymal cells). "Moreover, analyses of gene expression and DNA copy number showed that CCT2, CCT3, CCT5, CCT6A, and CCT7 are upregulated in GBM compared with normal brain tissue, while CCT2, CCT3, CCT5, CCT6A, and CCT8 display higher copy numbers than in low-grade gliomas." (PMID 41516249, 2025).
influenza (1 paper, 2020). An acute viral infection of the respiratory tract, occurring in isolated cases, in epidemics, or in pandemics; it is caused by serologically different strains of viruses (influenzaviruses) designated A, B, and C, has a 3-day incubation period, and usually lasts for 3 to 10 days. "Taken together, the involvement of CCT5 in influenza infection might be an important event that warrants our further study." (PMID 33178142, 2020). "Overall, our data suggest that CCT5 plays an important role in supporting influenza virus replication, which may hold the potential as an anti-influenza target." (PMID 33178142, 2020). "The obtained results suggested an important role of avian CCT5 in supporting influenza virus replication, which may serve as an anti-influenza target." (PMID 33178142, 2020). "In the present study, we provided evidence that avian CCT5 could interact with influenza PB2 and PB1 but not with PA." (PMID 33178142, 2020).
leiomyoma (1 paper, 2016). A well-circumscribed benign smooth muscle neoplasm characterized by the presence of spindle cells with cigar-shaped nuclei, interlacing fascicles, and a whorled pattern. "In addition, PTRF co-expresses with KRT1, CCT5 co-expresses with MHI1; GOT1 co-expresses with MHI1; and MHI1 co-expresses with LDHB; indicating not only an interaction between LDHB, GOT1 and MDH1, but also a possible association between them and the leiomyoma." (PMID 27070597, 2016).
microcephaly (1 paper, 2020). A congenital or acquired developmental disorder in which the circumference of the head is smaller than normal for the person's age and sex. "We identified the candidate genes PPARGC1A, CTBP1, TRIO, TERT, and CCT5 that are associated with the neuropsychomotor delay, microcephaly, and neurological alterations found in our patient." (PMID 32625234, 2020).
neuroblastoma (1 paper, 2010). Neuroblastoma (NB) is the most common solid, extracranial childhood tumor. "Products of other genes, i.e., RHOC, RHOA, CCT5 and TUFM, were reported as also being involved in cytoskeleton rearrangements that are necessary for changes of cell morphology during the neuronal differentiation of neuroblastoma cells." (PMID 20459794, 2010).
paraplegia (1 paper, 2019). Complete paralysis of the lower half of the body including both legs, often caused by damage to the spinal cord. "The protein CCT5 is involved incilia morphogenesis and neurodegenerative processes, and its deficiency maycause neurodegenerative diseases, such asspastic paraplegia, supporting the GO results." (PMID 30985858, 2019).
prostate carcinoma (1 paper, 2022). A carcinoma that arises from epithelial cells of the prostate gland. "No studies in prostate cancer have investigated the roles or the expressions of the T-complex protein 1 subunit epsilon, encoded by the CCT5 gene, or the trifunctional purine biosynthetic protein adenosine-3, encoded by the GART gene." (PMID 35562881, 2022).
retinal degeneration (1 paper, 2019). Degeneration of the retina. "Similar to our cct5 mutant, cct1, cct2, cct3, cct4 and cct8 mutant zebrafish show retinal degeneration, suggesting that the cct5/tcf7l1a double mutant phenotype is due to abrogation of TRiC chaperonin function, a conclusion supported by cct3 knockdown in tcf7l1a mutants." (PMID 30777146, 2019).
skin cutaneous melanoma (1 paper, 2025). "To determine whether genetic changes in CCT5 affect clinical outcomes in patients with cancer, we determined that the CCT5 mutation may be a protective factor for patients with skin cutaneous melanoma (SKCM)." (PMID 40274875, 2025).
tumor (21 papers, 2015 to 2026). "High CCT5 expression is associated with a poor prognosis in different tumor types, including HNSC, LUAD, BLCA, and KIRP." (PMID 40274875, 2025). "In this study, the expression of CCT5 was positively correlated with the infiltration of cancer-associated fibroblasts (CAFs) in numerous tumor types." (PMID 40274875, 2025). "Recently, accumulating evidence reveals that CCT5 was implicated in tumor progression, and high expression of CCT5 has been discovered in a range of malignancies and associated with worse survival." (PMID 37953237, 2023). "According to the results of this study, CCT5 was highly expressed in tumor tissues and was associated with a poor prognosis; hence, it was postulated that CCT5 could potentially function as an oncogene." (PMID 40274875, 2025). "Moreover, a high level of CCT5 in tumor tissues was significantly associated with 1-year, 3-year, and 5-year OS in HCC patients (all HR > 2.0, P < 0.001)." (PMID 34522182, 2021). "The genetic depletion of CCT5 suppressed epithelial proliferation, reduced dysplastic transformation, and limited tumor initiation in vivo." (PMID 41890968, 2026). "CCT2 and CCT5 have been shown to promote tumor invasion and metastasis by stabilizing the cytoskeleton." (PMID 41168872, 2025). "The results revealed significant CCT5 overexpression in most tumors and was significantly associated with poor OS and DFS in different tumor types." (PMID 40274875, 2025). "We used the TISCH2 database to investigate CCT5 expression in different cell types within the tumor microenvironment." (PMID 40274875, 2025). "CCT2 and CCT5 are two additional proteins found to decrease in abundance with increasing tumor severity." (PMID 41441336, 2025). "We suggest mechanistic insights into the role of CCT5 in tumorigenesis and tumor progression in the HCC population that should be considered in the future." (PMID 34522182, 2021). "CCT5 mRNA was significantly upregulated in tumor tissues compared with adjacent tissues in the GSE14520, GSE33006, GSE45436, GSE55092, GSE60502 and GSE101685 datasets (all P < 0.05)." (PMID 34522182, 2021). "As a target gene of miR-139-5p, CCT5 was overexpressed in HCC tumor tissues and peripheral blood mononuclear cells (all P < 0.05)." (PMID 34522182, 2021). "Western blots against recombinant CCT5 showed reactivity in 51% (23/45) of sera from patients with NSCLC but only 2.5% (1/40) of non-tumor individuals." (PMID 28969060, 2017). "The expression of CCT5 in tumors was significantly higher than that in the adjacent non-tumor tissue, which was confirmed by Western blot." (PMID 28969060, 2017). "Our observations compel us to propose that CCT5 may play a role in regulating the level of tumor-infiltrating immune cells, consequently affecting the prognosis of these tumors." (PMID 40274875, 2025). "CCT5 is highly expressed and upregulated in most tumors, indicating its tumor driver potency." (PMID 40274875, 2025). "Conversely, Plod2, Cdc20, and Cct5 genes were significantly upregulated in tumor tissues." (PMID 40018995, 2025). "The chaperonin containing TCP1 subunit 5 (CCT5) is believed to function as a tumor driver." (PMID 40274875, 2025). "Consequently, we comprehensively examined characteristics such as gene expression, proteomic expression, DNA methylation, survival analysis, genetic alteration, immune infiltration, and pathway analysis to characterize CCT5 in 33 TCGA tumor types." (PMID 40274875, 2025). "Thus, this study aimed to investigate the potential role of CCT5 as a prognostic biomarker and therapeutic target across all 33 tumor types in TCGA database, thereby elucidating its oncogenic role in various cancers." (PMID 40274875, 2025).
tumor (continued). "Therefore our study adds evidence to an important role of CCT3 and CCT5 in the more aggressive BRCA tumours: Basal, HER2 and Luminal B subtypes." (PMID 29954368, 2018). "Our results indicate that CCT5 is a potential tumor marker and may be useful in the diagnosis of NSCLC in an early stage." (PMID 28969060, 2017). "In the present study we identified four candidate tumor-associated antigens, including chaperonin containing TCP1 subunit 5 (CCT5), heat shock 70 kDa protein 8 isoform 1 (HSP70), eukaryotic translation elongation factor 1 gamma (eEF1), and phosphoglycerate mutase 1 (PGM1)." (PMID 28969060, 2017). "Together these findings suggest that expression of CCT5 in tumor tissue may be involved in tumor progression by inhibiting the function of TSPs, due to inactivated chaperonin." (PMID 28969060, 2017). "Furthermore, our findings suggest that CCT5 expression correlates with immune cell infiltration and may have a potential role in regulating the number of tumor-infiltrating immune cells." (PMID 40274875, 2025). "Interestingly, the proteins CCT5 and EEF1 in the subnetwork are known to be potential tumour-associated antigens that could be useful in the development of a diagnostic biomarker for NSCLC39." (PMID 32616892, 2020). "According to GSE32863 sequencing data, increased expression of CCT3, CCT4, CCT5, CCT6A, CCT7, and CCT8 was observed in LUAD tumor tissues compared with paired normal tissues." (PMID 39259093, 2024). "CCT5 mRNA was significantly overexpressed in HCC patients with alpha-fetoprotein (AFP) > 300 ng/ml, BCLC staging B-C, TNM staging III and main tumor size > 5 cm (all P < 0.05)." (PMID 34522182, 2021). "CCT5, LCOR, and ZNF367 were evidently overexpressed in tumor tissues compared with adjacent tissues (all P < 0.001), while FOS was significantly downregulated in tumor tissues compared with non-tumor tissues of HCC patients (P < 0.001)." (PMID 34522182, 2021). "Of this group of genes, HSPD1, HSPE1, CCT3 and CCT5 were overexpressed in Basal, HER2 and Luminal B subtypes (more aggressive BRCA tumours)." (PMID 29954368, 2018). "Anti-CCT5 autoantibody was found in 51% (23/45) of patients with NSCLC, but only 2.5% (1/40) in non-tumor individual controls." (PMID 28969060, 2017). "A negative correlation indicates that when CCT5 expression is higher in the tumor microenvironment, the NK cell infiltration level remains low." (PMID 40274875, 2025). "In summary, our results indicated that subunits of TRiC displayed varying degrees of abnormal expressions, and CCT2, CCT3, CCT5, CCT6A, CCT7, and CCT8 were significantly upregulated in BCa patients and their upregulation was positively correlated with BCa tumor stage." (PMID 33815471, 2021). "Additionally, CCT5 mRNA was significantly overexpressed in HCC patients with alpha-fetoprotein (AFP) > 300 ng/ml, BCLC staging B-C, TNM staging III and main tumor size > 5 cm (all P < 0.05)." (PMID 34522182, 2021). "Using immunohistochemical methods, we showed that higher expression of CCT5 tended to be localized only in the cytoplasm of tumor cells rather than in adjacent non-tumor tissues." (PMID 28969060, 2017). "For six of the genes (CCT5, CD72, COL10A1, FAM177A1, SLC25A12 and TDP1), we were unable to identify a correlation (i.e. concordance) between the copy number alteration and gene expression in six of the tumour samples tested." (PMID 25884485, 2015). "Data from the UALCAN database indicated that CCT4, CCT5, CCT6A, and CCT8 exhibited significantly higher promoter methylation in normal tissues than in tumor tissues, suggesting that low promoter methylation may be responsible for upregulating these CCTs in LUAD." (PMID 39259093, 2024). "However, the significance of CCT5 in various tumor types has not been extensively explored." (PMID 40274875, 2025).
tumor (continued). "However, a comprehensive pan-cancer analysis specifically focusing on CCT5 is currently lacking, although recent studies have suggested a strong link between the entire CCT gene family and tumor proliferation." (PMID 40274875, 2025).
cancer (17 papers, 2009 to 2025). A tumor composed of atypical neoplastic, often pleomorphic cells that invade other tissues. "In this investigation, we observed that CCT5 expression was associated with TMB in 9 cancer types and with MSI in 7 cancer types." (PMID 40274875, 2025). "In this study, we found that CCT5 was positively associated with immune checkpoint genes in 12 types of cancers, and a similar correlation was found in immune stimulating and inhibitory genes." (PMID 40274875, 2025). "Then, using the UALCAN database, we examined the variant expression levels of CCT5 in 24 cancer studies." (PMID 40274875, 2025). "Furthermore, we investigated the association between CCT5 genetic alterations and clinical outcomes in cancer patients." (PMID 40274875, 2025). "The findings of the drug sensitivity analysis indicated that CCT5 expression, which is linked to the efficacy of various drugs, may play a crucial role in the future development of targeted immunotherapies for cancers characterized by CCT5 expression." (PMID 40274875, 2025). "As CCT5 expression is associated with the sensitivity of these drugs, this investigation suggests that it may help to develop targeted immunotherapy in the future for any cancer associated with the expression of CCT5." (PMID 40274875, 2025). "Therefore, we used EPIC algorithms to examine the relationship between CCT5 expression in various cancers and cancer-associated fibroblasts, CD8 + T cells, and NK cell infiltration." (PMID 40274875, 2025). "In this study, CCT5 was strongly negatively associated with immune score in 10 types of cancer." (PMID 40274875, 2025). "The CCT5 structure harbors key functional domains, including a nucleotide-binding site, substrate-binding site, sensor loop, and apical loop, all of which are implicated in protein folding stability, a process linked to cancer pathogenesis." (PMID 40274875, 2025). "A different approach found that NSCLC patients produced auto-antibodies to CCT5 at higher levels than healthy individuals; so, screening for these auto-autoantibodies in sera could be a novel diagnostic for cancer." (PMID 35602608, 2022). "Further experimental and clinical studies are warranted to investigate CCT5’s practical application in cancer therapy and prognosis prediction." (PMID 40274875, 2025). "To analyze the potential role of CCT5 in pan-cancer, we used different publicly available databases that derived original data from TCGA databases." (PMID 40274875, 2025). "We utilized the UALCAN online resources to investigate the promoter methylation level of CCT5 in various types of cancer." (PMID 40274875, 2025). "Analysis of 16 probes from the SMART database was conducted across pan-cancers to investigate the methylation status of CCT5." (PMID 40274875, 2025). "We further investigated the expression pattern of CCT5 in GEPIA2 in multiple cancer studies and compared it with that in normal tissues." (PMID 40274875, 2025). "Correlation analysis revealed that CCT5 expression was significantly associated with TMB and MSI in various cancers." (PMID 40274875, 2025). "Several CCT subunits, such as CCT2, CCT3, CCT4, CCT5, CCT6A, and CCT7, have been implicated in cancer progression." (PMID 40867231, 2025). "Our comprehensive pan-cancer analysis of CCT5 revealed that it is widely overexpressed in various cancer types, and that its expression and genetic alterations are significantly associated with clinical outcomes in patients with certain tumors." (PMID 40274875, 2025). "We then examined the specific cancer-related functions of the TRiC subunit CCT5 in the SK-HEP1 HCC cell line by targeted overexpression and knockdown." (PMID 34676169, 2021).
cancer (continued). "Another group of chaperone genes, such as CCT6A, CCT4, TCP1, CCT5, PTGES3 and CCT7, were previously implicated in cancer cell proliferation and predicts poor prognosis in HCC36,37." (PMID 33431814, 2021). "Furthermore, evidence suggests a potential connection between CCT5 expression and various types of cancer, including lung, breast, gastric, esophageal, head and neck, and rectal cancers." (PMID 40274875, 2025). "This suggested that differential methylation of the CCT5 N-shore site may play a role in pan-cancer carcinogenesis." (PMID 40274875, 2025). "We analyzed the prognostic value and oncogenic role of CCT5 in multiple types of cancers." (PMID 40274875, 2025). "In addition, there was a significant relationship between increased CCT5 expression and advanced cancer stage, indicating invasive development." (PMID 40274875, 2025). "These collective data suggest that CCT5 expression exhibited widespread correlation with immunity in cancers and may influence survival through interactions with immune infiltration." (PMID 40274875, 2025). "Additionally, this study used only a bioinformatics approach that provided preliminary evidence linking CCT5 with cancer progression in various tumors." (PMID 40274875, 2025). "Our study emphasizes the role of CCT5 in providing prognostic information for various cancer types." (PMID 40274875, 2025). "Survival prognosis indicated that CCT5 may act as a potential biomarker for several cancer types." (PMID 40274875, 2025). "In addition, these findings indicate that CCT5 acts as an oncogene in cancer development and may be an indicator for use in clinical applications in cancer prognosis." (PMID 40274875, 2025). "Meanwhile, bioinformatics has deconstructed the probable processes of CCT5 and ELF1, but further investigation will be needed to clarify their biological role and impact on the cancer microenvironment in future studies." (PMID 37953237, 2023). "Among them, COL1A1, COL1A2, MT-CYB, CCT5, and PAPPA have been reported to be closely related to cancer." (PMID 35360863, 2022). "This study, using dedicated-microarrays containing 6864 genes previously known to be involved in cancer, allowed us to select 5 genes (LGALS4, ACS5, CLU, SRI and CCT5) with significant differential expression between tumors and normal tissue." (PMID 19903339, 2009). "We also evaluated the correlation between CCT5 and NK cells and found that most cancer types demonstrated a negative correlation." (PMID 40274875, 2025). "Endogenous CCT5 protein levels were previously shown to increase upon DCAF12 knockout in the A-375 cancer cell line, but the interaction could not be confirmed in our analysis using HEK293T cells." (PMID 38665159, 2024). "CCT1, CCT5, and FKBP4 showed significantly lower expression in the cancer patients compared to the healthy volunteers, whereas HSPA9 and TRAP1 showed a significantly higher expression in patients with cancer compared to the control group for the most cancer types." (PMID 34692733, 2021). "A significant positive correlation between CCT5 and CD8 + T cells has been observed in most cancer types; however, several studies have shown a negative correlation." (PMID 40274875, 2025). "CCT5 showed the strongest negative correlation with TMZ IC50 values among the 19 ANOIRGs and was a differential prognostic gene, which plays a potential cancer-promoting role in LGGs." (PMID 37114037, 2023).